ROR1 (ROR family WNT receptor 1)
Diseases named in the same sentence as ROR1 in open-access papers (continued):
Sharing a sentence is not in itself a finding about the gene and the disease.
pancreatic cancer (continued). "Anti-ROR1 monoclonal antibodies (mAbs) and ROR1 specific RNA interference (RNAi) molecules induced apoptosis and growth impairment of several types of malignant cells expressing ROR1 including pancreatic carcinoma." (PMID 29856777, 2018). "Here, the antitumor activity of KAN0439834 was explored in vitro using a panel of eight human pancreatic carcinoma cell lines expressing the phosphorylated full-length ROR1 and EGFR." (PMID 29856777, 2018). "Further studies are warranted of this novel therapeutic principle in pancreatic carcinoma as well as in other ROR1 expressing tumors alone and specifically in combination with other targeting drugs or standard of care." (PMID 29856777, 2018). "High ROR1 expression was detected in pancreatic cancer specimens with positive staining localized to the cytoplasm as well as the nucleus of cancer cells." (PMID 28811962, 2017). "Our ROR1 BiTE mediated antigen-specific cytotoxicity across a range of solid tumor cells including pancreatic cancer cell lines with concurrent cytokine production in vitro." (PMID 28811962, 2017). "We were unable to detect ROR1 expression in healthy pancreas but ROR1 was widely and strongly expressed by pancreatic cancer tissue." (PMID 26030772, 2015). "ROR1 heavily contributes to the aggressive nature of pancreatic cancer." (PMID 40869147, 2025). "Given ROR1′s role in maintaining cancer stemness and metastasis, approaches that effectively neutralize ROR1 activity or its upstream regulators hold significant promise for not only controlling primary tumor growth but also preventing recurrence in pancreatic cancer patients." (PMID 40869147, 2025). "A pancreatic cancer model was constructed using Panc02 pancreatic tumor cells with the type I receptor tyrosine kinase-like orphan receptor (ROR1) (Panc02/ROR1), which showed that valeric acid therapy increased the anti-tumor effectiveness of CAR-T cells in a pancreatic cancer model." (PMID 38302980, 2024). "Further preclinical and clinical studies are needed in order to establish the therapeutic potential that ROR1 BiTE could have on pancreatic cancer either alone or in combination with other treatments." (PMID 39759138, 2024). "A recent in vivo study demonstrated that CAR-T therapy modified to possess a receptor tyrosine kinase-like orphan 1 (ROR1) receptor induced a significant decrease in tumor volume and weight in a subcutaneous mouse model of pancreatic cancer featuring ROR-1-expressing Panc02 cells." (PMID 36765752, 2023). "Previous studies in diffuse large B-cell lymphoma (DLBCL) and small-cell lung cancer (SCLC) have indicated that combining ROR1 inhibitors with venetoclax or with erlotinib and chemotherapeutics in pancreatic carcinoma acted synergistically to induce tumor cell death." (PMID 36297673, 2022). "We further sought to determine, whether pentanoate pretreatment of ROR1-CAR T cells had a supportive effect on their anti-tumor reactivity in a pancreatic cancer model." (PMID 34210970, 2021). "Therefore, we generated ROR1-expressing Panc02 pancreatic tumor cells (Panc02/ROR1) and injected them s.c. into WT mice." (PMID 34210970, 2021). "Focusing initially on pancreatic cancer, we demonstrated that our ROR1 BiTE results in T cell mediated and antigen-specific cytotoxicity against ROR1-expressing pancreatic cancer cell lines in vitro at exceedingly low concentrations (0.1 ng/mL) and low effector to target ratios." (PMID 28811962, 2017). "However, our humanized ROR1 BiTE represents a rational therapy for cancer patients with high-unmet need such as those with aggressive tumors like pancreatic cancer and warrants further assessment in clinical trials." (PMID 28811962, 2017). "Ectopic expression of ROR1 is also observed in a wide variety of solid malignancies, tissue microarray analysis showed strong staining of ROR1 in 30 % or greater of primary samples in colon, lung, and pancreatic cancers." (PMID 26576539, 2015).
pancreatic cancer (continued). "The study also identified that knocking down ROR1 inhibited EMT and invasion of circulating tumor cells that were obtained from blood samples of patients who had pancreatic cancer." (PMID 38213538, 2023). "Given the overexpression of ROR1 in many solid tumors and the urgent need for targeted strategies for these entities, as well, KAN0439834 has already been tested for application in pancreatic cancer." (PMID 33445713, 2021). "In the present study, we analyzed the apoptotic effects of a first-in-class ROR1 small molecule, KAN0439834, targeting the TK domain of ROR1, in a panel of human pancreatic cancer cell lines." (PMID 29856777, 2018). "Apoptosis (Annexin V/PI) of the pancreatic cancer cell lines induced by KAN0439834 (500 nM) and the control anti-ROR1 mAb (10 μg/ml) were analyzed." (PMID 29856777, 2018). "In summary, a first-in-class small molecule active against phosphorylated ROR1, KAN0439834, was studied for killing capacity of pancreatic carcinoma cell lines." (PMID 29856777, 2018). "A study found that ROR1 expression was upregulated in pancreatic cancer tissue in comparison to adjacent noncancerous tissue." (PMID 38213538, 2023). "This reprogramming results in elevated production of effector molecules such as CD25, IFN-γ and TNF-α, and significantly enhances the anti-tumor activity of antigen-specific CTLs and ROR1-targeting CAR T cells in syngeneic murine melanoma and pancreatic cancer models." (PMID 34210970, 2021). "In addition, ROR1 was shown to be expressed in pancreatic cancer with no expression in normal pancreatic tissues." (PMID 29856777, 2018).
melanoma (22 papers, 2014 to 2025). A malignant, usually aggressive tumor composed of atypical, neoplastic melanocytes. "Research has shown that hypoxia can induce a switch in melanoma cells from a receptor tyrosine kinase-like orphan receptor 1 (ROR1)+ to a more invasive ROR2+ phenotype, which is associated with resistance to BRAF inhibitors." (PMID 40867277, 2025). "Another report on melanoma observed that ROR1 was associated with a poorly invasive phenotype, and its knockdown increased invasion in vitro as well as metastasis formation in vivo." (PMID 33445713, 2021). "Transcriptomic analysis of melanoma cell lines reveals that the expression of ROR1 is associated with a proliferative signature, but also correlates with a non-invasive phenotype." (PMID 24752542, 2014). "Akt is a well known effector of the Wnt5a pathway and both Wnt5a and ROR1 were consistently shown to promote Akt phosphorylation in several tumor types, including melanoma." (PMID 34774050, 2021). "For instance, in melanoma ROR1 knockdown was followed by increased expression of ROR2 and WNT5A, while the knockdown of ROR2 stimulated ROR1 expression, confirming a reciprocal regulation." (PMID 33445713, 2021). "During progression from dysplastic naevi to malignant melanoma, ROR1 expression goes down and the rate of cell division decreases in accordance with metastatic phenotype." (PMID 30832318, 2019). "Recently, ROR1 and ROR2 co-receptor upregulation was associated to the two different melanoma states: proliferative and invasive." (PMID 31921125, 2019). "The treatment of proliferative melanoma cells, expressing ROR1, with WNT5a induced ROR1 degradation, increased ROR2 expression and high invasiveness in vivo." (PMID 31921125, 2019). "Silencing ROR1 expression in melanoma significantly inhibits cell migration and invasion through decreasing expression of vimentin and N-cadherin." (PMID 28427197, 2017). "Inhibition of the RTK ROR1 by anti-ROR1 mABs and siRNA induced apoptosis of melanoma cells also has been reported." (PMID 27051190, 2016). "The expression of ROR1 is detected in multiple melanoma cell lines, as assessed by RT-PCR, Western blot, and flow cytometry." (PMID 24752542, 2014). "Within melanoma cell lines, treatment with anti-ROR1 mAb results in varying degrees of apoptosis, between 4% and 54%, which is dependent upon the specific anti-ROR1 mAb and melanoma cell lines." (PMID 24752542, 2014). "Interestingly, two of the cell lines in the present study (A375 and UACC903) were used to demonstrate that Wnt5a and ROR1 activate Akt suggesting that both ROR receptors have antagonistic roles on the activation of Akt in melanoma." (PMID 34774050, 2021). "In addition to cirmtuzumab, a second generation mAb targeting ROR1 has been created: 5F1-B10, which induced apoptosis in melanoma and bladder cancer cells by inhibiting pro-survival ROR1 signaling." (PMID 33445713, 2021). "In addition, aberrant expression of ROR1 and the consequences of this occurrence have been reported in pancreatic, breast, and ovarian cancers as well as melanoma." (PMID 30832318, 2019). "Silencing ROR1 in all melanoma cell lines tested induces apoptosis." (PMID 24752542, 2014). "Therefore, and considering the contribution of ROR1 to EMT in melanoma and as shown here in HCC, it is plausible to hypothesize that ROR1 activity can be a decisive point during carcinogenesis." (PMID 30832318, 2019). "Inverse to the impact of exogenous ARSB and pertinent to the development of melanoma, ARSB silencing increased CHST15 expression, abundance of C4,6S disaccharides, and activation of phospho(Tyr)-ROR1 and phospho(Ser473)-AKT1 and reduced nuclear FOXO3a and COP1 expression." (PMID 40562100, 2025). "In addition, whereas ROR2 expression is a marker of good prognosis (this manuscript), ROR1 was shown to correlate with poor melanoma survival, further supporting the opposite function of both ROR1 and ROR2 in melanoma." (PMID 34774050, 2021).
melanoma (continued). "Other than that, ROR1, FOXC1, MIF, TGFβ, lncRNA SNHG17, MIAT, MHENCR, OR3A4 and H19 regulate proliferation, progression, migration, invasion, metastasis or EMT-like transition though PI3K/AKT pathway in melanoma cells." (PMID 32333246, 2020). "Interestingly, silencing ROR1 leads to an increase in Wnt5a and ROR2 expression, supporting a more invasive phenotype of melanoma cells." (PMID 24752542, 2014). "This suggests that activation of noncanonical WNT5A-induced signaling and ROR1 and ROR2 changes is indeed a part of the melanoma adaptation mechanism to vemurafenib." (PMID 34702444, 2021).
lymphoma (21 papers, 2013 to 2025). A malignant (clonal) proliferation of B- lymphocytes or T- lymphocytes which involves the lymph nodes, bone marrow and/or extranodal sites. "NCT05279300 is a Phase 1a/b clinical trial involving a novel anti-ROR1 antibody drug conjugate which is tested on advanced solid tumors and lymphomas." (PMID 39551787, 2024). "A part of the HCL2025 project, created by the HCL Foundation and the Leukemia and Lymphoma Society, is dedicated to the study of ROR1 as a novel therapeutic target in HCL." (PMID 36620555, 2022). "In the lymphoma tissues, there were ROR1-negative cases as well as those with both cytoplasmic and membranous staining patterns for ROR1." (PMID 32586008, 2020). "Both ROR1 and ROR2 regulate β-catenin-independent signaling and have been associated with carcinogenesis and metastasis in several malignancies, including leukemias and lymphomas." (PMID 38791952, 2024). "While the existence of this mechanism of resistance to BTK inhibition remains to be confirmed in lymphoma patients, monitoring ROR1 expression may become an important component of managing lymphomas treated with a BTK inhibitor." (PMID 38638855, 2024). "Additionally, in vivo ROR1.ICOS.OX40ζ T-cells showed anti-lymphoma activity, a long-lasting central memory phenotype, improved overall survival, and evidence of long-term CAR T-cell persistence." (PMID 37719008, 2023). "In various lymphoid cancers, Zilovertamab Vedotin, an anti-ROR1 antibody coupled to the microtubule inhibitor Auristatin E, could achieve partial response in the subgroup of patients with mantle cell lymphoma and diffuse large cell B-cell lymphoma." (PMID 36982422, 2023). "Anti-ROR1-antibodies, for instance Cirmtuzumab have entered phase I trials in lymphoma." (PMID 36982422, 2023). "Another ROR1-targeted ADC, CS5001, achieved a 43.5% response rate in patients with advanced lymphomas." (PMID 40723210, 2025). "Receptor tyrosine kinase-like orphan receptor 1 (ROR1), emerges as a prime example of this kind of lymphoma-cell reprogramming." (PMID 38638855, 2024). "Various lymphoma antigens are amenable to CAR-T cell targeting, such as CD19, CD20, CD22, CD30, the kappa light chain, and ROR1." (PMID 39206402, 2024). "ROR1 and Lyn are important regulators of signaling pathways driving CLL and several lymphomas, namely MCL." (PMID 35295854, 2022). "CR was even observed in lymphoma cells without universal ROR1 expression, an effect that was attributed to the high toxicity of MMAE." (PMID 33445713, 2021). "In general, CD19CAR T cells become non-functional in CD19 negative lymphoma subsets; however, AdCAR T cells can be redirected to alternative target antigens beyond CD19, such as CD20, CD22, CD79B, and ROR-1." (PMID 36289682, 2022).
sarcoma (15 papers, 2015 to 2025). A usually aggressive malignant neoplasm of the soft tissue or bone. "ROR1 expression data in high-risk sarcoma, including Ewing sarcoma, osteosarcoma, alveolar or embryonal rhabdomyosarcoma, and fibrosarcoma, have been published, but none was found for liposarcoma." (PMID 38791952, 2024). "Our data indicate that IGF1R and ROR1 CAR T cells could be used as a potential therapy for high risk sarcomas." (PMID 26173023, 2015). "IHC staining demonstrated that thyroid carcinoma, sarcoma, and cholangiocarcinoma cases showed higher ROR1 prevalence and higher H-scores than other tumor types." (PMID 38791952, 2024). "Preclinical studies have also suggested a promising activity of CAR T cells targeting the type I insulin-like growth factor receptor (IGF1R) and the tyrosine–kinase-like orphan receptor 1 (ROR1), which are highly expressed in sarcoma cell lines." (PMID 37190214, 2023). "IGFR1 and ROR1 CAR-T cells derived from a sarcoma patient significantly suppressed tumor growth in both localized and disseminated sarcoma xenograft models." (PMID 33467481, 2021). "further demonstrated that ROR1 is highly expressed in sarcoma cell lines including EWS, osteosarcoma, rhabdomyosarcoma, and fibrosarcoma." (PMID 34566963, 2021). "They further found that ROR1-targeted CAR-T cells remarkedly suppressed sarcoma growth in pre-established localized and disseminated sarcoma xenograft models associated with prolonged survival." (PMID 34503279, 2021). "An adoptive transfer of IGFR1-CAR and ROR1-CAR T cells derived from a sarcoma patient significantly suppressed tumor growth in both localized and disseminated sarcoma xenograft models." (PMID 32326444, 2020). "Since IMC-3G3, a monoclonal antibody against PDGFRα, has been approved by FDA in treating sarcoma patients, it will be interesting to know if ROR1-positive cancer cells are more sensitive to PDGFR inhibition." (PMID 31137681, 2019). "Third, Both IGF1R and ROR1 CAR T cells derived from a sarcoma patient can significantly suppress sarcoma growth in both localized and disseminated pre-established sarcoma xenograft models." (PMID 26173023, 2015). "We also showed that adoptive transfer of IGF1R- and ROR1-specific CAR T cells from a sarcoma patient significantly reduced tumor growth in pre-established, systemic and localized sarcoma xenograft models." (PMID 26173023, 2015). "We demonstrated that Sleeping Beauty (SB) transposon-modified T cells with IGF1R- and ROR1-specific CARs were reactive against many types of sarcomas." (PMID 26173023, 2015). "ROR1 appears to be an attractive therapeutic target in sarcomas because of its limited expression in normal adult tissues." (PMID 26173023, 2015). "Altogether, these results firmly demonstrate that both IGF1R and ROR1 CAR T cells are cytotoxic to antigen+ sarcoma cells in vitro." (PMID 26173023, 2015). "This study was designed to evaluate chimeric antigen receptor (CAR) T cells targeting the type I insulin-like growth factor receptor (IGF1R) or tyrosine kinase-like orphan receptor 1 (ROR1) molecules for their therapeutic potential against sarcomas." (PMID 26173023, 2015). "The adoptive transfer of IGF1R and ROR1 CAR T cells derived from a sarcoma patient significantly reduced tumor growth in pre-established, systemically disseminated and localized osteosarcoma xenograft models in NSG mice." (PMID 26173023, 2015). "These experiments demonstrate that SB-engineered IGF1R and ROR1 CAR T cells from a sarcoma patient can function as antitumor effector cells in vivo." (PMID 26173023, 2015). "Altogether, these results demonstrate that SB engineered IGF1R and ROR1 CAR T cells derived from a sarcoma patient can suppress sarcoma growth in vivo." (PMID 26173023, 2015). "Next, we determined if SB modified IGF1R and ROR1 CAR T cells kill sarcomas in an antigen-specific manner." (PMID 26173023, 2015).